NDRG1 (N-myc downstream regulated 1)
Diseases named in the same sentence as NDRG1 in open-access papers (continued):
Sharing a sentence is not in itself a finding about the gene and the disease.
tumor (continued). "In addition, Li and Chen reported that NDRG1 plays vital roles in tumor metastasis suppression and is frequently silenced in metastatic colon cancers." (PMID 23874544, 2013). "N-myc downstream regulated gene (NDRG1) was described as a potential tumor suppressor gene in various human cancers, and could be associated with tumor aggressiveness and metastasis." (PMID 23899187, 2013). "Due to NDRG1’s known tumor-suppressive activity, the impairment of cell motility and invasion potential by eIF3a over-expression may be due to the ability of eIF3a to up-regulate the expression of NDRG1." (PMID 23437357, 2013). "The results of the present study suggest that monitoring SGK1 levels as well as responses of NDRG1 phosphorylation to Akt inhibitor administration could have a use in predicting the sensitivity of tumours to compounds that target Akt." (PMID 23581296, 2013). "This study extends our knowledge about the regulation of NDRG1 at the transcriptional level by tumor suppressive genes, and suggests that FOXD3 may be of potential values as a novel therapeutic target for NB." (PMID 24269992, 2013). "Consistent with this hypothesis, in studies using C-terminal directed anti-NDRG1 antibodies, both single and double bands have been observed in a range of human tumour cell-types." (PMID 23634903, 2013). "Reports have indicated that NDRG1 inhibits tumor growth and metastasis in several types of cancer." (PMID 23762858, 2013). "It is reasonable to assume therefore, that NDRG1 may act as a protective agent to affect tumor progression." (PMID 24260043, 2013). "Both oncogenic and tumour suppressive roles have been proposed for NDRG1." (PMID 23581296, 2013). "In addition, rescue experiments in FOXD3 over-expressed or silenced NB cells showed that restoration of NDRG1 expression prevented the tumor cells from FOXD3-mediated changes in these biological features." (PMID 24269992, 2013). "Our present study strongly supports the idea that whether NDRG1 promotes or suppresses the malignant progression of human cancer depends upon tumor types and/or differentiation status." (PMID 22844455, 2012). "The N-myc downstream-regulated gene 1 (Ndrg1) is a metastasis suppressor with anti-tumor function." (PMID 22295061, 2012). "NDRG1 knockdown suppressed the local invasion of As1/Mock3 tumor cells into the surrounding stroma and adjacent adipose and/or muscle tissue, and encapsulated tumor growth." (PMID 22844455, 2012). "These genes are involved in the regulation of immune/inflammatory response (Lgals1, Ptgds, Tff2, Ubd), tumor angiogenesis (Lgals1, Esm1, Ndrg1), epidermal growth factor signaling (Erbb4, Nrg1), response to tissue injury (Tff2, Vnn1), and gene transcription (Id3, Ifrd1)." (PMID 19340302, 2009). "In this study, we investigated whether NDRG1 is upregulated in these tumours, thus providing a novel marker for malignant cells in the pancreas." (PMID 16832411, 2006). "In serial sections, NDRG1 was colocalised only in well-differentiated tumour regions." (PMID 16832411, 2006). "However, pancreatic tissue obtained from tumour-free resection margins displayed strong staining for NDRG1 specifically in hyperplastic islets and hyperplastics ducts." (PMID 16832411, 2006). "NDRG1 is a very stable protein and has been proposed as an indicator of tumour hypoxia." (PMID 16832411, 2006). "Furthermore, NDRG1 is a highly stable protein and has been suggested as a prognostic marker for hypoxic regions within a tumour mass." (PMID 16832411, 2006). "This may account for the observed patchy pattern of NDRG1 expression we observed in moderately differentiated tumours." (PMID 16832411, 2006). "We hypothesised that NDRG1 may be a novel indicator of malignant cells in the pancreas as hypoxia is a general feature of these tumours." (PMID 16832411, 2006).
tumor (continued). "Therefore, despite the proposal of HIF-1 as a tumour marker, we present its down-stream product Ndrg1 as a stronger candidate of cancer marker especially for certain tissues (lung, brain, and skin)." (PMID 15341671, 2004). "Ndrg1 protein is a better indicator of tumour hypoxia than HIF-1 in immunohistochemical analyses." (PMID 15341671, 2004). "The observation of NDRG1 being down-regulated by a major tumour suppressor further supports our observation that it is up-regulated in several cancer tissues and could be used as a marker." (PMID 15341671, 2004). "Additionally, our previous findings suggest that not all TNBC patients may have active TGFβ-driven tumorigenic NDRG1, where NDRG1 could act as a tumor suppressor, making its inhibition undesirable in those patients." (PMID 40612674, 2025). "The association between nuclear staining and poorer outcome in our study may relate to the enhanced level of cellular stressors like genomic instability and hypoxia in aggressive tumours and metastases, but it is evident that more detailed investigation of nuclear NDRG1 is essential." (PMID 40530439, 2024). "Importantly, we observed that depletion of NDRG1 resulted in a proliferation advantage of BCa cells, comparable to the effect observed when perturbing expression of the well‐known tumour suppressor Rb1, indicating a role of NDRG1 as a tumour suppressor in BCa." (PMID 37854018, 2024). "Additionally, the NDRG1 gene can regulate tumor MVD, leading to a poor prognosis in HGG patients." (PMID 39668822, 2024). "Interestingly, 80% of TNBC cases switched to a gain of nuclear expression at the BrM stage, indicating that even though most of the TNBC tumours were positive for NDRG1 expression in both BC and BrM, there was a clear distinction in the localisation of NDRG1 expression." (PMID 40530439, 2024). "Given that it was initially suggested that the subcellular location of NDRG1, p-NDRG1 (Ser330, Thr346) could determine its pleiotropic effect in tumor cells 11, we questioned if TGFβ1 drives changes in the subcellular localization of NDRG1 and p-NDRG1 (Thr346)." (PMID 36594086, 2023). "Overexpressing NDRG1 could inhibit the function of PKCδ in promoting tumor invasion and migration." (PMID 36816970, 2023). "Tumour-like CAFs (tCAFs): We observed strong differential expression of proliferation-, migration- and metastasis-associated genes (e.g., PDPN, MME, TMEM158 and NDRG1) as well as stress-response-associated genes (e.g., ENO1), and GAPDH in a small cluster (n = 786 cells)." (PMID 37463917, 2023). "Given that TGFβ, Twist, and Vimentin also contribute to the generation of CSCs, drug resistance, and tumor progression 41,42, and because NDRG1 promotes chemoresistance 43, we explored whether TGFβ-driven NDRG1 could have a role on TNBC progression by modulation of CSCs." (PMID 36594086, 2023). "Similarly, the side population was modified only in SUM159 cells, although Multi-Drug Resistance 1 (MDR1), or p-glycoprotein, was reduced in both SUM159 and MDA-MB-231 cells only upon activation with TGFβ1, what endorses the notion that NDRG1 is involved in tumor chemoresistance." (PMID 36594086, 2023). "Notably, NDRG1 exhibited differential expression across different tissues, with minimal expression in any cell subtypes of normal tissues and higher expression in macrophages of tumor tissues, lymphoid tissues, and portal carcinoma plugs." (PMID 38235128, 2023). "Furthermore, the results of in vivo experiments such as in tumorous tissue of U251 tumor-bearing mice also showed that the acquisition of NDRG1 function repressed expression of EMT-related proteins and inhibited the development of tumor, proliferation, and migration." (PMID 35448004, 2022).
tumor (continued). "Although the exact cellular functions of this protein have not been elucidated, mutations in NDRG1 or aberrant expression of this protein have been associated with tumor-suppressive and oncogenic phenotypes, which collectively suggest that NDRG1 functions in a tissue-specific manner." (PMID 35448004, 2022). "The detection of markers suchas PLEKHA5 and NDRG1 in primary tumour biopsies could provide an earlyindication of aggressive phenotype, providing they can be fully validated.Practical limitations on prognostic biomarker translation are expertly reviewedelsewhere." (PMID 35225863, 2022). "However, the effects of NDRG1 on tumor invasion and the mechanisms behind it are rarely understood." (PMID 33994856, 2021). "Highly expressed IFIT2 and NDRG1 could reduce tumor migration and metastasis." (PMID 35096568, 2021). "Moreover, NDRG1 actively promotes β-catenin localization to the plasma membrane, where it acts as a component of the adherens junction, together with E-cadherin, to enhance cell-to-cell adhesion and inhibit tumor cell metastasis." (PMID 34572031, 2021). "Finally, we identified NDRG1 as a candidate downstream of HIF to suppress tumour progression." (PMID 32537867, 2020). "We hypothesized that NDRG1 might contribute to the inhibitory effect of HIF in tumour progression." (PMID 32537867, 2020). "Our study provided direct evidences that NDRG1 might be a tumour suppressor in ccRCC." (PMID 32537867, 2020). "Furthermore, NDRG1 has been demonstrated to upregulate the tumor suppressors PTEN and SMAD4." (PMID 31739170, 2019). "Furthermore, the expression of Ki-67 obviously decreased in the NDRG1 overexpression group, and increased in the SH-NDRG1 group, compared to their relative control groups, suggesting that NDRG1 significantly inhibited the tumor growth via activating p21 function." (PMID 31831018, 2019). "NDRG1 is clearly annotated as having multiple and wide ranging roles in cellular stress response, proliferation and growth arrest, and tumor progression and metastasis and a static prediction for its regulatory circuitry may not suffice for explaining its diverse roles." (PMID 30811403, 2019). "In addition, NDRG1 might promote tumour development via the EMT pathway by modulating SMAD4/slug expression." (PMID 30914736, 2019). "Hence, these results above suggested that combination of HER2-targeted agents with NDRG1 inducer, DpdtC may achieve greater anti-tumor effects via more effectively inhibiting the phosphorylation of ERK1/2 and downstream signaling pathway." (PMID 29467385, 2018). "Notably, our previous results showed that NDRG1 expression was increased in OS and this elevation was correlated with tumor progression and prognosis, suggesting that NDRG1 could be considered as a promising therapeutic approach in OS." (PMID 28906492, 2017). "In addition, NDRG1 inhibited tumor growth and promoted apoptosis in mouse xenograft model." (PMID 28537875, 2017). "Thus, reducing the expression of NDRG1 can decrease tumor growth rate." (PMID 27148394, 2016). "However, it remains unclear whether NDRG1 can modulate tumor progression by acting on progenitor cells, including macrophages." (PMID 26778110, 2016). "Importantly, this agent has been demonstrated to upregulate the potent metastasis suppressor, N-myc downstream-regulated gene-1 (NDRG1), which inhibits the epithelial to mesenchymal transition and results in suppression of oncogenic signaling, tumor cell migration, and metastasis in vivo." (PMID 27678372, 2016). "Thus, the anti-tumor efficacy of sorafenib may in part be mediated through its indirect inhibition of NDRG1 expression and functions." (PMID 26359353, 2015). "Interestingly, NDRG1 was found to suppress the stress-induced autophagic response, which could mediate the anti-tumor and anti-metastatic activities of NDRG1 by enhancing apoptosis and inhibiting metastasis." (PMID 26125440, 2015).
tumor (continued). "The anti-tumor activity of NDRG1 was demonstrated to be mediated by preventing β-catenin nuclear translocation, as silencing of this latter molecule could reverse the effects of silencing NDRG1 expression." (PMID 26418878, 2015). "In summary, for the first time, we have demonstrated that FOXD3 is down-regulated in human NB, and FOXD3 exhibits tumor suppressor activity that affects the growth, invasion, metastasis, and angiogenesis of NB cells in vitro and in vivo through direct transcriptional regulation of NDRG1." (PMID 24269992, 2013). "However, it remains unclear why NDRG1 functions as tumor suppressor or promoter depending upon tumor types or histological types." (PMID 22844455, 2012). "Recombinant MIF alone similarly suppressed NDRG1 and enhanced survival, highlighting its dual role as both a mediator of WISP1 activity and an independent tumor-promoting factor." (PMID 41597235, 2026). "Conversely, NDRG1 exhibits context-dependent functional reversal in HCC, where it significantly suppresses HCC tumorigenesis and metastasis by inducing tumor cell ferroptosis." (PMID 40823093, 2025). "On the other hand, we found an enrichment of hypoxia related terms for NMF_4 and NMF_5 with the top genes VEGFA, NDRG1, and ENO1, markers of previously reported “MES-hypoxia” tumor cell state." (PMID 40781324, 2025). "In this latter study, it was revealed that, similar to NDRG1, NDRG2 mRNA and protein levels were increased in several tumor cell lines exposed to hypoxia." (PMID 40378957, 2025). "Our previous work showed that phosphorylation of NDRG1 is regulated by ECM and adhesion receptors leading to the enrichment of pNDRG1-positive cells near tumor-stroma interfaces in PDAC SW1990 xenografts." (PMID 40654607, 2025). "This suggests that the role of NDRG1 in autophagy and UPR is context-dependent and should be considered in relation to specific cell and tumour types." (PMID 40332138, 2025). "A schematic model illustrates how NDRG1‐mediated lactate accumulation promotes M2 macrophage polarization and inhibits CD8+ T cell activity, further enhancing the immunosuppressive tumor microenvironment and reducing the efficacy of immunotherapy." (PMID 40539245, 2025). "To investigate the cooperative role of NDRG1 and LDHA in glycolysis, we first examined how NDRG1 affects glucose uptake and mitochondrial function in tumor cells." (PMID 40539245, 2025). "To investigate the role of NDRG1‐induced lactate production in tumor progression, we established a subcutaneous LLC tumor model." (PMID 40539245, 2025). "The analysis results showed that the expression levels of G6PD, KIF20A, NDRG1, RECQL4, and MCM4 were significantly higher in HCC tumor tissues than in normal tissues, while ADH1C was significantly downregulated in HCC tumor tissues." (PMID 41169384, 2025). "NDRG1 is often regarded as a potential metastasis suppressor gene, with studies indicating that NDRG1 can inhibit EMT in the initial stages of metastasis, thereby exerting an inhibitory effect on tumor metastasis." (PMID 40151835, 2025). "This study aims to evaluate the role of intra-tumor microvessel density (MVD) (as a surrogate measure of angiogenesis), VM, and NDRG1 in UC and their correlation with different clinicopathologic features, then assess the correlation between them in UC." (PMID 38561462, 2024). "Localisation changes were compared across BC and BrM and revealed that HER2+ cases were more likely to gain cytoplasmic and membranous NDRG1 expressions, whereas ER+ and TNBC tumours showed a nuclear gain." (PMID 40530439, 2024). "We also identified additional potential regulators of BLM epithelial tumor differentiation such as CDX2 and NDRG1." (PMID 38893159, 2024). "Thus, NDRG1 could play a major role in the angiogenic on- or off-switch of tumor stroma." (PMID 38561462, 2024). "Related studies have shown that NDRG1 gene affects the prognosis of GBM mainly by affecting the NF- κ B signal pathway and then affecting the expression of VM in tumor." (PMID 39668822, 2024).
tumor (continued). "Consistent with tumour grade, HER2+ and TNBC showed a higher proportion of cases with nuclear NDRG1 expression compared with ER+ cases, which consisted of 62% of non‐nuclear NDRG1 cases in BC and BC‐BrM patients." (PMID 40530439, 2024). "Seven genes passing these filters were involved in various aspects of tumour biology, including cell survival and DNA repair (CASP9, NDRG1, and XPA), mTOR signalling (TSC1), and transcription and RNA processing (ETV6, ISY1, and SMAD2)." (PMID 39660592, 2024). "The mean of intra-tumor MVD, VM area, and NDRG1 was significantly higher in tumors with higher grade, lymphovascular invasion, and higher T stage." (PMID 38561462, 2024). "In contrast to NDRG1, NDRG2 acts as a tumor suppressor, inhibiting proliferation and cell survival via regulations of MAPK/STAT3, cyclin-D1, β-catenin, NF-κB, E-cadherin, and other signaling pathways." (PMID 38611020, 2024). "Recurrent samples were enriched in mesenchymal-like tumor cells (“MES”), expressing high levels of NDRG1 and VEGFA that further distinguish them as hypoxic." (PMID 38805346, 2024). "In contrast to NDRG1, we found that NDRG2 expression was higher in normal samples than in tumor samples (p < 0.0001)." (PMID 38611020, 2024). "Afterward, it was found that NDRG1 exacerbates HCC initiation via enhancing crosstalk between fibroblasts and tumor cells and promotes the growth of HCC cells by interacting with GSK-3β and Nur77 to prevent β-catenin degradation." (PMID 37406019, 2023). "Single-cell analysis dissected that ERRFI1, ETS1, NDRG1, and ZMAT3 were expressed in the tumor microenvironment." (PMID 37600707, 2023). "Knockdown of NDRG1 inhibits the survival, proliferation and migration of HCC cells, and NDRG1 plays a promoting role in tumor progression." (PMID 37208604, 2023). "The results demonstrated that compared with the control group, the tumor size and number of HCC lung metastases were markedly decreased after NDRG1 knockdown." (PMID 37208604, 2023). "As a potent inhibitor of oncogenic signaling in PaC, NDRG1 was found to limit the production of cytokines and growth factors that influence the TME, consequently reducing tumor progression and inhibiting metastasis." (PMID 37345116, 2023). "To further explore the regulatory role of NDRG1 in the growth and tumor metastasis of HCC, we constructed a xenograft tumor model of LM3 cells and a tail vein lung metastasis model." (PMID 37208604, 2023). "Previous studies reported that high NDRG1 expression correlates with poor patient survival in aggressive, inflammatory, and TNBC by using publicly available gene datasets and/or tumor tissue specimens 9,17,18,26." (PMID 36594086, 2023). "NDRG1 also suppressed the RAS-RAF-MEK-ERK cascade by increasing the expression levels of SMAD4, another well-studied tumor suppressor." (PMID 37345116, 2023). "Then, we constructed a xenograft tumor model of LM3 HCC cells, and the results showed that knockdown of NDRG1 significantly inhibited the tumorigenic ability of HCC cells in nude mice and induced the ferroptosis of HCC cells." (PMID 37208604, 2023). "We found that NDRG1 maintains TGFβ-induced CSCs, specifically ALDH1+ in all cell lines and CD44+/CD24- and side population in primary-tumor-derived cells." (PMID 36594086, 2023). "NDRG1 is a member of the 4 NDRG gene family determined to suppress oncogenesis and tumor progression in different cancers such as breast, prostate, brain, colon, pancreas, and rectum." (PMID 37970212, 2023). "For example, known HCC-related genes (NDRG1 and VEGFA) are among the most highly expressed genes in the “tumour” clusters." (PMID 35109839, 2022). "Our xenograft animal study illustrates that CAPE treatment effectively attenuated tumor growth in vivo by downregulating MALT1 and upregulating NDRG1 expression in PC-3 cells." (PMID 35053438, 2022).